AURKC (aurora kinase C)
Description:
Serine/threonine-protein kinase component of the chromosomal passenger complex (CPC), a complex that acts as a key regulator of mitosis. The CPC complex has essential functions at the centromere in ensuring correct chromosome alignment and segregation and is required for chromatin-induced microtubule stabilization and spindle assembly. Also plays a role in meiosis and more particularly in spermatogenesis. Has redundant cellular functions with AURKB and can rescue an AURKB knockdown. Like AURKB, AURKC phosphorylates histone H3 at 'Ser-10' and 'Ser-28'. AURKC phosphorylates the CPC complex subunits BIRC5/survivin and INCENP leading to increased AURKC activity. Phosphorylates TACC1, another protein involved in cell division, at 'Ser-228'.
Synonyms: AIE2; AIK3; ARK3; STK13; AurC; HEL-S-90; SPGF5; aurora-C
Tractability: Small molecule: a drug acting on it is in phase 2 or 3 trials; a structure with a bound ligand is known; a high-quality ligand is known; it belongs to a druggable protein family. PROTAC: ubiquitination databases record sites on it; a small molecule that binds it is known.
Target class: Other protein kinase AUR family; Other protein kinase group; Enzyme; Kinase; Protein Kinase
Chemical probes: AMG-900 (high quality), Aurora-compound 1 (high quality), DANUSERTIB, FMF-01-086-2 (high quality), FMF-03-145-1 (high quality), FMF-04-159-2 (high quality), PD081660, PD082811
Safety:
Unwanted effects reported when the protein is acted on. In parentheses: how it was acted on, where the effect was seen, and who reports it.
heart disease (cardiovascular system; source: Force et al. (2011))
Gene: Protein-coding gene on chromosome 19 (57,231,009 to 57,235,551, forward strand). Ensembl gene ENSG00000105146.
Subcellular location: Nucleus; Chromosome; Chromosome, centromere; Cytoplasm, cytoskeleton, spindle
Gene Ontology:
Molecular function: protein binding; protein kinase activity; protein serine/threonine/tyrosine kinase activity; ATP binding; protein serine kinase activity; protein serine/threonine kinase activity
Biological process: protein phosphorylation; attachment of spindle microtubules to kinetochore; mitotic spindle midzone assembly; mitotic spindle organization; positive regulation of cytokinesis; positive regulation of mitotic cell cycle spindle assembly checkpoint; positive regulation of mitotic cytokinesis; regulation of cytokinesis; regulation of cell cycle process; spindle assembly
Cellular component: condensed chromosome; midbody; spindle midzone; centrosome; chromosome passenger complex; kinetochore; spindle; spindle microtubule; spindle pole; chromosome; chromosome, centromeric region; nucleus
Genetic constraint (gnomAD): Loss-of-function variants: 17 observed, 31.62 expected, observed/expected ratio (o/e) 0.54, 90% interval 0.37 to 0.81. The upper end of that interval is the gene's LOEUF score, 0.81, which puts it in group 3 of 6, group 1 being the genes least tolerant of losing a copy. Missense variants: 332 observed, 399.56 expected, observed/expected ratio (o/e) 0.83, 90% interval 0.76 to 0.91. Synonymous variants: 150 observed, 157.25 expected, observed/expected ratio (o/e) 0.95, 90% interval 0.83 to 1.09.
Gene-disease validity (ClinGen):
ClinGen rates the evidence that AURKC causes each of these diseases.
spermatogenic failure 5 (autosomal recessive): Definitive. A male infertility due to sperm disorder characterized by the presence, in sperm, of a very high percentage of spermatozoa with enlarged head, irregular head shape, multiple flagella, and abnormal midpiece and acrosome.
Homologues: Orthologues: chimpanzee AURKC (99% identical), dog AURKC (85% identical), rabbit AURKC (84% identical), rat Aurkc (73% identical), mouse Aurkc (71% identical), guinea pig AURKC (67% identical). Paralogues in human: AURKB (76% identical), AURKA (64% identical).
Diseases named in the same sentence as AURKC in open-access papers:
AURKC is named in the same sentence as 32 diseases in open-access papers, as found by Europe PMC text mining. Sharing a sentence is not in itself a finding about the gene and the disease. The quoted sentences say what the papers report.
macrozoospermia (10 papers, 2017 to 2026). "For example, the homozygous mutation (c.144delC) of the AURKC gene is the main cause of macrozoospermia (a rare male infertility disorder); in a Tunisian study, the prevalence of this mutation in infertile men was 0.4%." (PMID 41602861, 2026). "Other mutations in men with macrozoospermia have been identified in AURKC gene, such as p.C229Y, p.Y248, and c436-2A>G." (PMID 38790229, 2024). "“Macrozoospermia” is characterized by large-headed spermatozoa with multiple flagella and is often due to mutations of Aurora Kinase C (AURK) gene that ensures efficient meiosis." (PMID 36303645, 2022). "The relationship between sperm morphology and aneuploidies is interesting also for systematic sperm defects such as in case of macrozoospermia caused by AURKC mutations." (PMID 36303645, 2022). "A second patient was suffering from macrozoospermia, and he carried the recurrent AURKC mutation found in the North African population." (PMID 33809228, 2021). "WES analysis of the patient with macrozoospermia from a consanguineous family allowed the identification of a novel homozygous missense variant in the AURKC gene (c.269G>A)." (PMID 30594972, 2019). "This study expands the spectrum of AURKC mutations and helps guide the practitioners to make optimal decisions for patients with macrozoospermia." (PMID 30594972, 2019). "Currently, the most relevant single-gene defect that has been identified in a patient with macrozoospermia is a mutation in Aurora Kinase C (AURKC)." (PMID 30594972, 2019). "In one patient with macrozoospermia, a homozygous pathogenic variant was identified in AURKC." (PMID 39180390, 2025). "Until now, only five mutations of AURKC have been described to be associated with macrozoospermia: c.144delC (p.L499Wfs22), c.744C>G (p.Y248*), c686G>A (p.C229Y), c.930+38G>A (occurs in the 3′-UTR), and c.436-2A>G (splicing site mutation that leads to the skipping of exons 5)." (PMID 30594972, 2019). "To date, this is the sixth reported variant in the AURKC gene associated with macrozoospermia." (PMID 30594972, 2019). "In the last decade, five mutations (c.144delC (p.L49Wfs22), c.744C>G (p.Y248*), c686G>A (p.C229Y), c.930+38G>A (occurs in the 3′-UTR), and c.436-2A>G (splicing site mutation that leads to the skipping of exons 5)) in the AURKC gene have been reported to be associated with macrozoospermia." (PMID 30594972, 2019). "In addition, new AURKC mutations that cause macrozoospermia have been reported." (PMID 29259455, 2017). "The AURKC gene, expressed in male germ cells and involved in chromosomal segregation and cytokinesis, was the first recognised genetic alteration in men with macrozoospermia (deletion c.144delC, recently renamed c.145delC)." (PMID 38790229, 2024). "In addition to AURKC, other genes, such as ZMYND15, NUP210L, MEIKIN, ADAD2, and MDC1, might be involved in macrozoospermia, albeit mutations in these genes have been identified in a few case reports." (PMID 38790229, 2024).
breast carcinoma (6 papers, 2012 to 2025). "Because AURKC is overexpressed in breast cancer cells, its PPI networks provide valuable information regarding its contribution to oncogenesis." (PMID 29050234, 2017). "In this study, we identified IκBα as a PPI partner protein of AURKC, as well as a small-molecule inhibitor that targets the AURKC–IκBα interaction and interferes with the growth and tumorigenic activity of breast cancer cells." (PMID 29050234, 2017). "In this study, with the goal of elucidating the mechanistic role of AURKC in cancer cell transformation, we identified IκBα as a novel AURKC binding partner and an inhibitor capable of targeting the AURKC–IκBα interaction in breast cancer cells." (PMID 29050234, 2017). "Colony-forming assays revealed that IκBα is essential for AURKC-induced transformation in MDA-MB-231 breast cancer cells." (PMID 29050234, 2017). "Based on our results, the AURKC–IκBα interaction represents a promising therapeutic target for treatment of breast cancer." (PMID 29050234, 2017). "The CT genes, OIP5, TAF7L, and AURKC have been identified as biomarkers for breast cancer and may be promising and potent candidates for therapeutic cancer vaccines." (PMID 36967804, 2023). "AURKC is overexpressed in invasive breast cancer cells and exerts oncogenic activity, but the precise underlying mechanisms remain unknown." (PMID 29050234, 2017). "Recent studies demonstrated that AURKC activation contributes to breast cancer cell transformation." (PMID 29050234, 2017). "To determine whether AKCI exerts an anticancer effect by targeting AURKC protein in MDA-MB-231 breast cancer cells, we performed migration, invasion, and colony formation assays." (PMID 29050234, 2017). "Thus, IκBα might be involved in AURKC-induced transformation in AURKC-overexpressing breast cancer cells." (PMID 29050234, 2017). "Thus, the small-molecule inhibitor AKCI represents a first step towards developing targeted inhibitors of AURKC protein binding, which may lead to further advances in the treatment of breast cancer." (PMID 29050234, 2017). "In silico modeling and computational analyses revealed a small-molecule inhibitor (AKCI) that blocked the AURKC–IκBα interaction and exerted antitumor activity in MDA-MB-231 breast cancer cells." (PMID 29050234, 2017). "We also found that AURKC is not a “common essential” gene; however, its lower incidence of amplification/overexpression in breast cancer reduced its therapeutic potential for inducing CIN in a large percentage of tumors." (PMID 39826695, 2025). "Survival analysis using the univariate Cox PH model with single gene expression shows that AURKB, but not AURKC, expression is significantly related to patient survival in five breast cancer data sets." (PMID 23228031, 2012). "Therefore, AURKC is both a promising marker and therapeutic target for breast cancer; however, its signaling network has not been fully characterized." (PMID 29050234, 2017).
male infertility (5 papers, 2012 to 2022). The inability of the male to effect fertilization of an ovum after a specified period of unprotected intercourse. "In humans, homozygous AURKC mutation is associated with male infertility, but women carrying this mutation were reported to be fertile." (PMID 33725274, 2021). "Several genetic mutations, including PRM1, AURKC, SPATA16, PICK1, DPY19L2, SEPT12, and SEPT14, result in male infertility and are caused by sperm DNA damage in a clinical context." (PMID 36295569, 2022). "There are also male infertility cases caused by defects in single genes including CFTR, DDX3Y, SYCP3, TEX11, AURKC, and DPY19L2, but the number of genes confidently linked to male infertility remains very low." (PMID 34190021, 2022). "The absence of AURKC causes male infertility owing to the production of large-headed multiflagellar polyploidy spermatozoa." (PMID 22046184, 2012).
colorectal cancer (3 papers, 2014 to 2021). A primary or metastatic malignant neoplasm that affects the colon or rectum. "Furthermore, overexpression of AURKC has also been detected in human colorectal cancers, thyroid carcinoma, and several cancer cells." (PMID 34066975, 2021). "Expression of AURKC is downregulated by PLZF, a transcriptional repressor, through recruitment to its promoter region, and it is of interest to note that the expression levels of PLZF and AURKC mRNAs display opposite patterns in human cervical and colorectal cancers." (PMID 25097550, 2014).
cervical cancer (2 papers, 2011 to 2015). A primary or metastatic malignant neoplasm involving the cervix. "Moreover, CEBPD can induce genomic instability through the activation of AURKC expression in response to inflammatory signals in cervical cancer." (PMID 26307680, 2015).
gastric cancer (2 papers, 2019 to 2024). A primary or metastatic malignant neoplasm involving the stomach. "It has been shown that single nucleotide polymorphisms in AURKC were associated with cancer risk in both glioblastoma and gastric cancer." (PMID 38322990, 2024). "The results of this study revealed that AURKA (rs1047972 and rs911160), AURKB (rs2241909 and rs2289590) and AURKC (rs11084490) polymorphisms could affect the risk of gastric cancer, both individually and synergistically." (PMID 31521144, 2019). "We examined rs11084490 in AURKC and its potential relationship with gastric cancer risk." (PMID 31521144, 2019). "In this study, SNPs rs2273535, rs1047972, rs911160 and rs8173 (AURKA), rs2241909 and rs2289590 (AURKB), rs758099 and rs11084490 (AURKC), and rs42873 (PLK1) mitotic kinases were screened for associations with the genetic susceptibility to gastric cancer (GC) in Bosnian population." (PMID 31521144, 2019).
glioblastoma (2 papers, 2021 to 2024). The most malignant astrocytic tumor (WHO grade IV). "The results of the present study demonstrated that AURKB (rs2289590) and AURKC (rs11084490) polymorphisms reduce the risk of glioblastoma multiforme development." (PMID 34465813, 2021).
glioma (2 papers, 2020 to 2022). A benign or malignant brain and spinal cord tumor that arises from glial cells (astrocytes, oligodendrocytes, ependymal cells). "Because of striking morphological changes (data not shown) in glioma cells depleted of either aurora kinase A, aurora kinase B, or aurora kinase C, we investigated the function in vitro." (PMID 34058053, 2022).
ovarian carcinoma (2 papers, 2016 to 2020). A malignant neoplasm originating from the surface ovarian epithelium. "Therefore, BRDT-mediated ovarian cancer cell progression is associated with regulation of PLK1 and AURKC expression." (PMID 33257688, 2020). "The results of the current study show that PLK1 and AURKC are expressed in ovarian cancer cells." (PMID 33257688, 2020). "Importantly, BRDT-KO-induced anti-ovarian cancer cell activity was largely attenuated with PLK1 and AURKC re-expression." (PMID 33257688, 2020).
prostate carcinoma (2 papers, 2016 to 2022). A carcinoma that arises from epithelial cells of the prostate gland. "Aurora kinase family members AURKA, AURKB and AURKC, have key functions to control mitotic progression in normal cells and are frequently overexpressed and dysregulated in several forms of cancer, including prostate cancer, contributing to progression of the disease." (PMID 35853811, 2022).
asthma (1 paper, 2023). "Furthermore, DNAm markers in HOXA7 and HOXA4 genes have been associated with lung development and asthma, while DNAm in AURKC has been associated with lung function in Latino children with asthma." (PMID 36979655, 2023).
Breast tumors (1 paper, 2017). "Breast tumors express significantly higher levels of AURKC than normal breast tissues, and the AURKC gene is amplified in MDA-MB-231 cells." (PMID 29050234, 2017). "Breast tumors often significantly overexpress AURKC in comparison with normal breast tissues." (PMID 29050234, 2017).
clear cell carcinoma (1 paper, 2025). "The protein expression levels of AURKC were evaluated in clear cell carcinoma and adjacent normal tissues, followed by prognostic analysis." (PMID 39895780, 2025).
clear cell renal cell carcinoma (1 paper, 2025). "In this study, the specific role of AURKC in renal clear cell carcinoma and its mechanism was investigated." (PMID 39895780, 2025).
HIV-1 infection (1 paper, 2022). The type species of lentivirus and the etiologic agent of acquired immunodeficiency syndrome (AIDS). "In this sense, a recent investigation showed that epigenetic changes in aurora kinase B (AURKB) and aurora kinase C (AURKC) are involved during the early stages of HIV-1 infection." (PMID 35628408, 2022).
invasive breast carcinoma (1 paper, 2017). A carcinoma that infiltrates the breast parenchyma. "MDA-MB-231 is an invasive breast cancer cell line, and its growth rate increases rapidly when AURKC is overexpressed (data not shown)." (PMID 29050234, 2017).
malignant peritoneal mesothelioma (1 paper, 2025). An aggressive malignant mesothelioma that arises from the peritoneum. "Recently, pediatric malignant peritoneal mesothelioma cases have been genetically studied, with alterations observed in ALK, EWSR1, FUS1, YY1, or in AURKA, AURKC, HLA-1B, ZNF-217, OR5F1, and MEN1 genes, but not in BAP1." (PMID 40725095, 2025).
myeloid leukaemia (1 paper, 2021). "To assess the potential effect of the AURKB/C inhibitor GSK1070916 on myeloid leukaemia metastases in human ovarian tissue, we first used Western blot analysis to examine AURKB and AURKC expression levels in a panel of six myeloid leukaemia cell lines and in human ovarian cortex." (PMID 33725274, 2021).